SENP2 (SUMO specific peptidase 2)
Diseases named in the same sentence as SENP2 in open-access papers (continued):
Sharing a sentence is not in itself a finding about the gene and the disease.
bladder cancer (7 papers, 2015 to 2023). "SENP2 inhibits TGFβR1 SUMOylation, thus suppressing TGFβ-induced epithelial to mesenchymal transition in bladder cancer." (PMID 37332576, 2023). "SENP2 overexpression in invasive bladder cancer cells, T24, suppresses TGFβ-mediated SMAD2/3 phosphorylation, downregulates the expression of mesenchymal markers N-cadherin and fibronectin, and inhibits epithelial to mesenchymal transition." (PMID 37332576, 2023). "The expression of SENP2 in bladder cancer patients is reduced, leading to attenuation of its suppressive effects on tumor progression." (PMID 31842336, 2019). "As a result, bladder cancer patients with reduced SENP2 expression have a greater chance for the development of more aggressive tumors and poor outcomes." (PMID 31842336, 2019). "On the other hand, recent studies of SENP2 in bladder cancer showed that the expression of SENP2 is downregulated in bladder cancer cells, causing an increase of MMP13 for cell migration and invasion." (PMID 29955155, 2018). "The effects of SENP2 on bladder cancer invasion are partially mediated by inhibiting the expression of MMP13." (PMID 27178176, 2016). "SENP2 appeared to inhibit bladder cancer cells migration and invasion in vitro, through suppressing MMP13 in BC cells." (PMID 26369384, 2015). "SENP2 appeared to inhibit migration and invasion of bladder cancer cells in vitro, through suppressing MMP13 in BC cells." (PMID 26369384, 2015). "However, SENP2 functions as a tumor suppressor in bladder cancer by limiting the expression of MMP13 and inhibiting the invasion and migration of bladder cancer." (PMID 33273928, 2020). "Moreover, SENP2 functions as a tumor metastasis suppressor in bladder cancer." (PMID 27178176, 2016). "This process is reversed by SENP2 (SUMO-specific protease-2), which removes SUMO from TGFBR1, thereby inhibiting TGF-β1-induced EMT, resulting in inhibition of the invasion of bladder cancer cells in vitro and tumor metastasis in vivo." (PMID 31842336, 2019). "Consistent with this notion, this research group found that SENP2 could desumoylates TGF-β RI receptor but not Smad4 in bladder cancer cells." (PMID 29955155, 2018).
hepatocellular carcinoma (6 papers, 2014 to 2024). A malignant tumor that arises from hepatocytes. "SENP2 has been described as a prognostic marker in bladder, breast or hepatocellular cancer, and in osteosarcoma." (PMID 39152119, 2024). "SENP2 has been reported to play a crucial role in hepatocellular carcinoma (HCC) cell growth by modulating β-catenin stability." (PMID 33968766, 2021). "Small ubiquitin-like modifier specific peptidase 2 (SENP2) suppresses the progression and chemoresistance of several cancers, while few studies report its role in hepatocellular carcinoma (HCC)." (PMID 34950583, 2021). "SENP2 has been reported to play a critical role in the control of hepatocellular carcinoma (HCC) cell growth by modulating the stability of β-catenin." (PMID 27178176, 2016). "SENP2 has been shown to be involved in hepatocellular carcinoma cell growth by modulating the stability of β-catenin." (PMID 24926368, 2014). "SENP2, a deSUMOylation enzyme, was downregulated in hepatocellular carcinoma (HCC) tissues." (PMID 35847921, 2022).
osteosarcoma (6 papers, 2021 to 2024). A usually aggressive malignant bone-forming mesenchymal neoplasm, predominantly affecting adolescents and young adults. "Small ubiquitin-like modifier-Specific Protease 2 (SENP2) is a tumor suppressor that also has a good inhibitory effect on osteosarcoma." (PMID 38978960, 2024). "SENP2, which has a de-SUMOylating activity, is downregulated in both osteosarcoma tissues and MG63 osteosarcoma cell line." (PMID 35465332, 2022). "SOX9 knockdown greatly reduces the proliferation and invasiveness of the SENP2 knockout osteosarcoma cells." (PMID 36078118, 2022). "SENP2 regulates the proliferation, migration, and invasion of osteosarcoma cells via the degradation of SOX9, and in this way, it exerts its tumor suppressor function." (PMID 35465332, 2022). "SENP2 expression is also significantly decreased in osteosarcoma compared with adjacent normal tissue." (PMID 36078118, 2022). "SENP2 overexpression inhibits osteosarcoma cell proliferation, migration, and invasion, while SENP2 knockout by CRISPR-Cas9 has the opposite effect." (PMID 36078118, 2022). "SENP2 produces osteosarcoma inhibitory effects by directly binding and inhibiting Sox9." (PMID 38978960, 2024). "For example, studies on SENP2 have shown that the enzyme is downregulated in osteosarcoma cells, as well as in primary cancer tissues, and the induction of SENP2 results in reduced proliferation, migration, and invasion in osteosarcoma." (PMID 38534381, 2024). "This study suggests that SENP2 acts as an osteosarcoma suppressor by destabilizing SOX9." (PMID 36078118, 2022). "Using the CRISPR/Cas9 technique, scientists also demonstrated that SENP2, which was expressed at lower levels in primary human osteosarcoma tissue and cell lines, may be a potential target for osteosarcoma treatment." (PMID 33546657, 2021). "If SUMOylated, SOX9 cannot be ubiquitinated and degraded, making the activity of SENP2 necessary for SOX9 degradation and the consequent reduced osteosarcoma cell proliferation, thus characterizing this SENP as a tumor suppressor." (PMID 38534381, 2024).
Obesity (5 papers, 2016 to 2024). Accumulation of substantial excess body fat. "Overexpression of muscle-specific Senp2 alleviates high-fat diet-induced obesity and insulin resistance." (PMID 39588331, 2024). "Adipocyte‐specific knockout of SENP2 confers resistance to diet‐induced obesity." (PMID 39355507, 2024). "Similarly, liver-specific knockout of Senp2 in mice confers to resistance to hepatic steatosis and obesity induced by a high-fat diet." (PMID 39588331, 2024). "In conclusion, in view of the fact that increasing the SUMOylation in skeletal muscle can enhance energy expenditure, inhibiting SENP2 expression could serve as a novel therapeutic approach to alleviate obesity and hyperlipidemia." (PMID 39588331, 2024). "Importantly, the overexpression of SENP2 in muscles alleviates HFD-induced obesity and insulin resistance, demonstrating the biological significance and therapeutic potential of SENP2 activity in vivo." (PMID 32781719, 2020). "Additionally, mice lacking SENP2 demonstrate resistance to hepatic steatosis and obesity induced by a high‐fat diet." (PMID 39355507, 2024).
viral infection (4 papers, 2020 to 2025). "Upon viral infection, SENP2 deSUMOylates STING, which facilitates STING degradation in terminating this signaling." (PMID 35795661, 2022). "How SENP2 selectively functions in the late phase of viral infection is unknown." (PMID 33105828, 2020). "The study also found that the SUMO1 specific peptidase 2 (SENP2) deSUMOylates cGAS and STING at the late phase of viral infection or DNA stimulation, which conditions them for subsequent degradation by the ubiquitin-proteasomal or chaperone-mediated autophagy." (PMID 33105828, 2020). "Thus, TRIM38/SENP2 controls both cGAS and STING protein stability in the early and late stages of viral infection to ensure the timely activation and inactivation to fine-tune the pathway responses." (PMID 35795661, 2022).
lung carcinoma (3 papers, 2015 to 2024). "In addition, the expression of SENP2 displayed an inverse correlation with the immuno-checkpoint biomarker PD-L1 in a pilot collection of aggressive lung carcinomas." (PMID 39152119, 2024). "Moreover, SENP2 is frequently overexpressed in lung cancer due to the prevalence of the 3q26-29 amplicon." (PMID 34503213, 2021). "Thus, amplified PIAS1 and SENP2 are potential therapeutic targets in lung cancer, whereas the expression level of PIAS3 may predict sensitivity towards select treatments." (PMID 34503213, 2021). "In addition to lung cancer, amplifications of 3q26 are also frequent in other epithelial cancers, including head and neck cancer, cervical cancer, and ovarian cancer, which may indicate for SENP2 amplification." (PMID 34503213, 2021). "The network of SENP2, DCUN1D1, DVL2, and UBXN7 regulates proliferation of lung cancer cells that carry the 3q26-29 amplicon, as knockdown of any of the four proteins leads to inhibition of growth." (PMID 34503213, 2021).
diabetes (2 papers, 2023 to 2025). "SENP2 modulates diabetes-associated lipid metabolism through regulating the deSUMOylation of SET domain bifurcated 1 (Setdb1)." (PMID 40078991, 2025). "However, certain compounds, like Gingko extract, N106 (specific for SUMO-activating enzyme E1 ligase), or SENP2 inhibitors, like 1,2,5-Oxadiazole, can modulate SUMOylation and may be beneficial in diabetes." (PMID 37947589, 2023).
glioblastoma (2 papers, 2021 to 2025). The most malignant astrocytic tumor (WHO grade IV). "Moreover, UBE2I, UBA2, PIAS3, and SENP1 were highly expressed in glioblastoma, whereas PIAS1, RANBP2, SENP5, and SENP2 were downregulated in glioblastoma." (PMID 33898460, 2021). "PIAS1, RANBP2, SENP5, and SENP2 were downregulated in glioblastoma." (PMID 33898460, 2021). "As can be seen from the figure, UBE2I, UBA2, PIAS3, and SENP1 were upregulated in glioblastoma, whereas PIAS1, RANBP2, SENP5, and SENP2 were downregulated in glioblastoma." (PMID 33898460, 2021).
Glucose intolerance (2 papers, 2022 to 2025). Glucose intolerance (GI) can be defined as dysglycemia that comprises both prediabetes and diabetes. "The Senp2-βKO mice exhibited severe glucose intolerance compared to the control mice after 12 weeks of HFD feeding." (PMID 35064188, 2022). "However, Senp2-BKO mice exhibited increased systemic glucose intolerance after being on the HFD for 13 weeks, as determined by an intraperitoneal (i.p.)glucose tolerance test." (PMID 40579429, 2025).
Hepatic fibrosis (2 papers, 2019 to 2023). The presence of excessive fibrous connective tissue in the liver. "Our RNA-seq analysis revealed that SENP2 S344 phosphorylation plays a negatively regulatory role in pulmonary fibrosis idiopathic signaling and hepatic fibrosis/hepatic stella cell activation pathways, suggesting its involvement in regulating fibrotic changes." (PMID 37711550, 2023). "Another piece of work placed the deSUMOylating enzyme SENP2 as a critical protein to attenuate CCl4-induced liver fibrosis in mice by inducing activated HSC apoptosis via suppression of Wnt/β-catenin signaling program." (PMID 31817258, 2019). "SENP2 protein and mRNA expression levels were found to be decreased both in vitro and in vivo in activated hepatic stellate cells (HSCs) during the CCl4-induced liver fibrosis mouse model, being those levels restored after removal of the damage stimulus." (PMID 31817258, 2019). "Moreover, the Z-score (a measurement of activation) from IPA suggests that fibrotic changes-related processes in the pulmonary fibrosis idiopathic signaling pathway and hepatic fibrosis signaling pathway are positively upregulated in SENP2 S344A KI MLECs compared to WT MLECs after L-flow." (PMID 37711550, 2023). "Finally, the expression of the Wnt/β-catenin pathway members was downregulated upon SENP2 overexpression in TGF-β-activated HSCs, thus suggesting a therapeutic role of SENP2 in liver fibrosis." (PMID 31817258, 2019).
lung adenocarcinoma (2 papers, 2013 to 2023). A carcinoma that arises from the lung and is characterized by the presence of malignant glandular epithelial cells. "In addition, there are some genes in other modules that can have very important roles in lung adenocarcinoma, namely DLGAP5, BIRC5, PSMD2, Src, TTK, SENP2, PSMD2, DOK2, FUS among others." (PMID 23874428, 2013).
myocardial infarction (2 papers, 2021 to 2022). Gross necrosis of the myocardium, as a result of interruption of the blood supply to the area, as in coronary thrombosis. "Postnatal increase of SENP2 expression seems to play an important role in the inhibition of CM proliferation since mice with SENP2 deficiency exhibit improved cardiac function after myocardial infarction due to increased CM proliferation and angiogenesis." (PMID 34869605, 2021). "SENP2 deficiency could also moderate cardiac remodeling and better cardiac function after myocardial infarction." (PMID 35431915, 2022). "Inhibition of Akt deSUMOylation by SENP2 can raise cardiomyocyte proliferation and angiogenesis to improve cardiac function after myocardial infarction." (PMID 35431915, 2022). "Redox sensing SENPs, i.e. SENP1 and SENP3 obviously play a role in ROS dependent ischemia reperfusion injury of the heart, and a striking significance emerges for SENP2 in regulating cardiomyocyte proliferation and cardiac regeneration after myocardial infarction." (PMID 34869605, 2021).
nephrotic syndrome (2 papers, 2024). A collection of symptoms that include severe edema, proteinuria, and hypoalbuminemia; it is indicative of renal dysfunction. "The nKPC-EV-induced up-regulation of both SUMO1 and SENP2 in urine-derived podocytes was confirmed by RT-PCR, where the up-regulation reached significance in three podocytes lines from nephrotic syndrome patients." (PMID 38464119, 2024).
placental insufficiency (2 papers, 2016 to 2018). Failure of the placenta to deliver an adequate supply of nutrients and oxygen to the fetus. "Another example shows that extraembryonic expression of the SUMO-specific protease 2 (SENP2) is required for normal heart development, and that the cardiac defects that occur with inactivation of SENP2 are secondary to placental insufficiency." (PMID 29962966, 2018). "However, if SENP2 is deleted in the endothelial cells in the fetus, the AV cushions are normal indicating that the heart defects are secondary to placental insufficiency alone." (PMID 29962966, 2018). "Our findings here strongly argue against a specific requirement of SENP2 in cardiac tissue during heart development as we find that the heart deformities associated with global inactivation of SENP2 are not primary but secondary defects due to placental insufficiency." (PMID 26883797, 2016).
triple-negative breast carcinoma (2 papers, 2018 to 2024). An invasive breast carcinoma which is negative for expression of estrogen receptor (ER), progesterone receptor (PR), and human epidermal growth factor receptor 2 (HER2). "Moreover, our results suggest that the interaction and desumoylation between SENP2 and Smad4 promote cell migration in triple-negative breast cancer cells." (PMID 29955155, 2018).
type 2 diabetes (2 papers, 2020 to 2022). "Although SENP2 had been associated with type 2 diabetes, its role in regulating insulin secretion remained unclear." (PMID 35064188, 2022). "The region on Chr C2 near SNPs 5 and 6, contained four known genes (TRA2B, CHCHD4, IGF2BP2 and SENP2) but none of these genes contained disease-associated protein-coding changes, despite TRA2B and IGF2BP2 having association with type 2 diabetes in other species." (PMID 33228033, 2020).
adrenal hypoplasia (1 paper, 2022). "This shows that even in the absence of adrenal hypoplasia, Senp2 ablation results in a block of zF transdifferentiation from zG cells." (PMID 36543805, 2022).
Adrenal insufficiency (1 paper, 2022). Insufficient production of steroid hormones (primarily cortisol) by the adrenal glands. "To unravel new SUMOylation-sensitive pathways that could explain further the adrenal insufficiency of mice lacking SUMO protease SENP2, we performed bulk RNA sequencing on four-week-old male and female WT and Senp2cKO." (PMID 36543805, 2022).
Anxiety (1 paper, 2020). Intense feelings of nervousness, tension, or panic often arise in response to interpersonal stresses. "These analyses suggest that SENP2 knockout results in changes of gene transcription that are associated with various behaviors including locomotion, learning and memory, anxiety." (PMID 32290845, 2020). "Taken together, our results indicate that SENP2 plays an important role in the forebrain, and its absence leads to molecular and behavioral changes associated with locomotion, anxiety, learning and memory." (PMID 32290845, 2020). "As the SENP2 cKO mice exhibit decreased anxiety-like behavior, we attempted to screen out the genes associated with anxiety-like behavior from DEGs." (PMID 32290845, 2020). "Consistently, RNA-seq results showed that the loss of SENP2 is associated with moderate changes in gene transcripts related to “locomotion”, “learning and memory” and multiple gene expression changes associated with anxiety-related behavior." (PMID 32290845, 2020). "This SENP2 conditional knockout mice model may help reveal novel mechanisms that underlie a variety of neuropsychiatric disorders associated with anxiety and cognition." (PMID 32290845, 2020). "Moreover, using several different behavioral assays, we identified a reduced anxiety phenotype in the SENP2 cKO mice." (PMID 32290845, 2020). "Our observation also showed that SENP2 ablation decrease anxiety-like behavior." (PMID 32290845, 2020). "In this study, we generated conditional knockout of SENP2 in excitatory neurons in the postnatal forebrain and determined that these cKO mice display comprehensive behavioral phenotypes including hyperactivity, reduced anxiety-like behavior, impaired learning and memory." (PMID 32290845, 2020).
anxiety disorder (1 paper, 2021). A category of psychiatric disorders which are characterized by anxious feelings or fear often accompanied by physical symptoms associated with anxiety. "Targeting PIASxα and SENP2 to alter the SUMOylation of 5-HT1ARs could have important clinical relevance for the therapeutic intervention for anxiety disorders, as well as other neuropsychiatric disorders in which 5-HT1ARs are implicated." (PMID 34947973, 2021).
bone osteosarcoma (1 paper, 2020). A usually aggressive malignant bone-forming mesenchymal neoplasm arising from the bone. "In human bone osteosarcoma epithelial cells (U-2 OS), it has been shown that SENP2 shuttles continuously between the nucleus and the cytoplasm, where it is degraded by the 26S ubiquitin proteasome." (PMID 32994335, 2020).
breast tumor (1 paper, 2013). "We also discovered a negative correlation between SENP2 and GLUT1 in human breast tumor samples, which might indicate a role of SENP2 in regulating glucose metabolism in vivo." (PMID 23691130, 2013). "Negative correlation was found between SENP2 and GLUT1 protein in 30 breast tumor tissues." (PMID 23691130, 2013).
cardiac ischemia (1 paper, 2019). "Indeed, SENP1, SENP2 and SENP5, as well as SENP3, have each been strongly implicated in cardiac ischemia/reperfusion so it is likely that distinct subsets of SUMOylated proteins are regulated by different SENPs." (PMID 30973885, 2019).
cardiomyopathy (1 paper, 2021). A disease of the heart muscle or myocardium proper. "In transgenic mice with cardiac-specific SENP2 expression, overexpressed SENP2 leads to ASDs and VSDs, reduced proliferation of cardiomyocytes, and induced cardiomyopathy with aging." (PMID 34638970, 2021).